DOK2 (docking protein 2)
Diseases named in the same sentence as DOK2 in open-access papers (continued):
Sharing a sentence is not in itself a finding about the gene and the disease.
tumor (27 papers, 2003 to 2025). "It is also possible that loss of DOK2 on its own or in combination with loss of other tumor suppressors (e.g. DUSP4 which is located with DOK2 in the same frequently deleted locus at 8p21.3) is able to trigger a robust activation of the MAPK pathway hence favoring lung tumorigenesis." (PMID 24255704, 2013). "However, EGFR mutation can nonetheless induce tumor formation in the presence of an apparently intact DOK2 gene." (PMID 24255704, 2013). "We made a subcutaneous B16-hgp100 tumor injection and 10 days after we performed an adoptive cell transfer of WT and Dok1/Dok2 DKO CD8+ T cells." (PMID 38956389, 2024). "DOK2 is a well-known tumor suppressor gene in solid tumors and a member of the downstream protein DOK family of tyrosine kinases." (PMID 36139261, 2022). "DOK2 was demonstrated to be a tumor suppressor, where its overexpression inhibited the tumor-forming ability of EGFR mutant LUAD cells and its loss led to oncogenic EGFR-driven tumorigenesis in vivo." (PMID 34944063, 2021). "We found that low expression levels of ITK, and DOK2 in LUAD were associated with poor prognosis, possibly affecting tumor progression via the transmembrane receptor PTK signaling pathway." (PMID 32775050, 2020). "A study has found that DOK2 is a tumor suppressor gene in LUAD and that knocking out Dok2 in mice accelerates lung tumorigenesis induced by oncogenic EGFR." (PMID 32775050, 2020). "We monitored tumor formation and progression in Dok2 wild-type or Dok2 KO (-/-) C/EGFRDEL bitransgenic mice using magnetic resonance (MR) imaging at intervals over the course of one year." (PMID 24255704, 2013). "In our study, both IL4R and CXCR4 gene expressions were decreased with tumor progression, whereas both DOK2 and IL2RG gene expressions were increased with tumor progression." (PMID 23451142, 2013). "We then analyzed the effect of DOK2 expression on tumor formation after subcutaneous xenograft into immunocompromised mice." (PMID 24255704, 2013). "The ability of DOK2 to inhibit EGF-induced activity of wild-type RAS and the fact that DOK2 is constitutively bound to RASA1 in cells harboring EGFRL858R suggest that at least part of DOK2’s tumor suppressive function is to suppress RAS activation via RASA1." (PMID 24255704, 2013). "DOK2 expression inhibited tumor formation and partially suppressed EGF-induced RAS activation in NCI-H1975 cells." (PMID 24255704, 2013). "Finally, common among these two lists were the tumour suppressor genes DOK2 and PHLPP1 that demonstrated increased gene expression in response to dual inhibition of EZH2 and DNMTs in MM cells and lower expression in MM patient plasma cells compared to NPCs." (PMID 40866476, 2025). "Building on these results, we hypothesized that DOK1 and DOK2 invalidation in CD8+ T cells may be a promising approach to improve their anti-tumor functions and thus subsequent immunotherapy." (PMID 38956389, 2024). "DOK2, a known lung cancer tumour suppressor, is also differentially methylated in chemoresistant samples, further implicating altered methylation patterns of tumour suppressor genes in developing resistance to chemotherapy in HGSOC." (PMID 34885103, 2021). "Growing evidence indicates that DOK2 may be a promising tumor biomarker." (PMID 25435967, 2015). "We then investigated the role of DOK1 and DOK2 in physiology, TCR signaling and activation of naïve and primed CD8+ T cells and cytotoxic capacity against tumor cells." (PMID 38956389, 2024). "Within this region, there are established tumor suppressors (DLC1, DOK2 and LZTS1), as well as potential tumor suppressor genes (CSMD1, MTUS1, and MSR1), and many other genes not established in cancers." (PMID 35994499, 2022). "The vast majority of immune-related genes are strongly correlated with DOK2 in AML and other cancers, suggesting a wide variety of effects on the immunological activities of the tumor microenvironment." (PMID 35321466, 2022).
tumor (continued). "DOK2, GBP4, PSMB9, and NLRC5 were significantly changed according to methylation subgroups, survival, tumor stages, and T categories and were positively correlated, which was validated in the testing group (P < 0.05)." (PMID 36268281, 2022). "CD8A, DOK2, CX3CR1, TYROBP, CXCL9, CD300LF, and IFNG were identified as significant DEGs between tumor samples with high and low CD200R1 expression." (PMID 32635224, 2020). "For example, DOK2 lies telomeric to DUSP4, a MAP-kinase phosphatase which negatively regulates MAPK signaling downstream of RAS and has been identified as a candidate tumor suppressor gene." (PMID 24255704, 2013). "Two of these, CBX7 and EGR1, have well-described tumor suppressor functions, and recently DOK4 family members (DOK1, DOK2, and DOK3) were identified as lung tumor suppressors." (PMID 21375733, 2011). "DOK2 expression was confirmed in the normal colorectal mucosa tissues, which is consistent with the literature, whereas 34 out of 102 (33.3%) tumor specimens were negative." (PMID 25435967, 2015). "At very early time points less than 3 months post-doxycycline administration we did observe an increase in tumor number in Dok2 KO mice (data not shown)." (PMID 24255704, 2013). "Dok2 KO mice without EGFR expression displayed many fewer tumor nodules at this age than C/EGFRDEL mice, indicating that Dok2 loss likely cooperates in a synergistic manner with oncogenic EGFR." (PMID 24255704, 2013).
cancer (8 papers, 2013 to 2025). A tumor composed of atypical neoplastic, often pleomorphic cells that invade other tissues. "Numerous reports showed that the downregulation of DOK2 is associated with cancer development." (PMID 37395176, 2023). "In addition to its crucial role in molecular pathways, DOK2 is also associated with the prognosis of several cancers." (PMID 35321466, 2022). "To further understand how DOK1 and DOK2 regulate CD8+ T cell activity and especially their cytotoxic function against cancer cells, we crossed Dok1/Dok2 DKO mice with pmel-1 TCR transgenic mice." (PMID 38956389, 2024). "In the present study, DOK2 expression exhibited heterogeneity in pan-cancer analyses, which implied its inconsistent roles in different tissues." (PMID 35321466, 2022). "Among some genes associated with disease and immunity, DOK2 and TIMM17A are related to cancer, LMODI is linked to hypoperistalsis, MAVS is essential for virus-activated signaling pathways, and DOCK8 is linked to humoral immunity." (PMID 36139261, 2022). "We also similarly presented the correlations of DOK2 with these immune-related signatures in pan-cancer from the TISIDB database." (PMID 35321466, 2022). "We hypothesized that depletion of intracellular inhibition checkpoint DOK1 and DOK2 could improve CD8+ T-cell based cancer therapies." (PMID 38956389, 2024). "The TCGA pan-cancer analysis depicted DOK2 mRNA expression in numerous tumors vs. normal tissues." (PMID 35321466, 2022). "We hypothesize that DOK2 may play varying roles in different cancers, leading to opposing survival trends." (PMID 35321466, 2022). "Downregulated DOK2 expression was found in 8 carcinomas (all P < 0.001)." (PMID 35321466, 2022). "In contrast, DOK2 expression was upregulated in 10 carcinomas, including AML (all P < 0.001)." (PMID 35321466, 2022). "To understand how DOK1 and DOK2 regulate CD8+ T cell activity and especially their cytotoxic function against cancer cells, we crossed Dok1/Dok2 DKO mice with pmel-1 TCR transgenic mice." (PMID 38956389, 2024). "The GSCA webtool provided correlations between DOK2 expression level and drug IC50 data from the Genomics of Drug Sensitivity in Cancer (GDSC) database." (PMID 35321466, 2022). "DOK2 was positively correlated with the majority of these immune markers irrespective of AML or other cancer types, which confirmed its vital role in a wide diversity of immune modulation." (PMID 35321466, 2022). "Together our data support a model in which loss of DOK2 impairs negative feedback on oncogenic signaling, leading to enhanced EGFR-RAS signaling and cancer." (PMID 24255704, 2013).
adenocarcinoma (1 paper, 2015). A common cancer characterized by the presence of malignant glandular cells. "The results showed that the negative expression of DOK2 was significantly more likely to be observed in the well- and moderately-differentiated adenocarcinomas than positive DOK2 expression." (PMID 25435967, 2015). "The two samples of poorly-differentiated adenocarcinoma were negative for DOK2 expression, however, the expression level in the four samples of moderately-differentiated adenocarcinoma was high." (PMID 25435967, 2015). "No DOK2 immunoreactivity was observed in the remaining samples from the 34 patients (33.3%) with poorly-differentiated adenocarcinoma." (PMID 25435967, 2015).
hematologic neoplasms (1 paper, 2022). "Herein, we noticed that DOK2 was conspicuously overexpressed in AML cell lines and other hematologic neoplasms, with significant hypomethylation levels." (PMID 35321466, 2022).
DOK2 also shares sentences with these, for which no sentence is quoted: eczema (2 papers); gastric adenocarcinoma (2); infection (2); acute leukemia (1); astrocytoma (1); basal cell carcinoma (1); Crohn disease (1); epilepsy (1); esophageal motility disorder (1); Latent infections (1); lymphoma (1); malignant skin tumors (1); measles (1); metastatic colorectal cancer (1); multiple myeloma (1); renal carcinoma (1); tendinopathy (1); ulcerative colitis (1).